IL1B (interleukin 1 beta)
Diseases named in the same sentence as IL1B in open-access papers (continued):
Sharing a sentence is not in itself a finding about the gene and the disease.
prostate carcinoma (continued). "Moreover, IL‐1β‐expressing cells created an MME that supported bone metastasis formation also by prostate cancer cells that do not express IL‐1β." (PMID 32761606, 2021). "Moreover, it was shown that the overexpression of IL-1b in non-metastatic prostate cancer cells promoted bone metastasis, whereas the knockdown of IL-1b impaired the bone progression of metastatic cells." (PMID 29890702, 2018). "Bone fragments cultured with PC-3 cells showed significantly higher values of OPG and TNF-α expression compared to bone fragments cultured without prostate cancer cells, both in normoxic and hypoxic conditions, while IL-1β expression was significantly higher, only under normoxic condition." (PMID 27765913, 2016). "Our previous work on bone metastasis specimens from 10 patients with prostate cancer showed that ARPOS cells harvested by laser capture microdissection and analyzed by RT-PCR completely lacked IL1β transcript." (PMID 36561929, 2022).
Thrombosis (109 papers, 2012 to 2026). "In case of JAK2V617F mutation, IL‐1β secretion is significantly increased compared with normal controls, involving in thrombosis." (PMID 40607626, 2025). "IL-1β increases the susceptibility to arterial thrombosis by promoting the NETosis-dependent release of the tissue factor." (PMID 38067137, 2023). "Recently, the Canakinumab Anti-inflammatory Thrombosis Outcome Study trial has proven that targeting IL-1β effectively reduces cardiovascular disease risk and mortality in patients with inflammation." (PMID 31938053, 2020). "Additionally, venous thrombosis in CD39-deficient mice was reduced by IL-1β blockade with a neutralizing IL-1β antibody or with an inhibitor of the IL-1 receptor." (PMID 39100675, 2024). "IL-1β and IL-18 are closely associated with venous thrombosis." (PMID 35937062, 2022). "Additionally, increased NLRP3-dependent IL-1β maturation and venous thrombosis is seen in mice deficient for the vasculoprotective enzyme CD39, which is reversed by IL-1 inhibition." (PMID 33391283, 2020). "NLRP3 and cleaved caspase-1 expression were significantly elevated in the atrium of MS patients with thrombus strongly indicating that for the first time, and to the best of our knowledge, that NLRP3 inflammasomes were activated and IL-1β was associated with thrombosis in MS patients." (PMID 26930272, 2016). "The secretion of IL-1β and IL-18 ultimately facilitates leukocyte and platelet recruitment, increases vascular permeability, exacerbates inflammation, and promotes venous thrombosis." (PMID 40520933, 2025). "Conversely, the Canakinumab Anti-inflammatory Thrombosis Outcomes Study demonstrated that interleukin-1β (IL-1β) antagonist canakinumab reduced the rate of recurrent CV events in patients with a prior MI and elevated hs-CRP levels." (PMID 40547439, 2025). "In the present investigation, we found that OP effectively suppressed the activation of TLR4/NF-κB and reduced the levels of inflammatory markers such as TNF-α, IL-1β and IL-6 in liver and lung tissues of mice with carrageenan-induced thrombosis." (PMID 40276603, 2025). "A landmark study, the Canakinumab Anti-inflammatory Thrombosis Outcome Study (CANTOS) trial highlighted the importance of IL-1β as a key therapeutic target for cardiovascular diseases." (PMID 39556309, 2025). "Canakinumab Anti-inflammatory Thrombosis Outcomes Study (CANTOS) showed that IL-1β inhibition by a monoclonal antibody substantially reduced cardiovascular disease risk." (PMID 39518478, 2024). "The possible role of inflammasomes in thrombosis has been outlined in a recent study showing that NLRP3 inflammasome activation and subsequent IL-1β production enhance venous thrombosis in response to hypoxia." (PMID 36674682, 2023). "In studying the relationship between the incidence of thrombosis and the levels of IL-1β and sP-selectin, there was a statistically significant correlation between serum levels IL-1β and sP-selectin concerning the occurrence of thrombosis in COVID-19 patients." (PMID 36522776, 2022). "Specifically, IL-1β is a key accelerator of venous thrombo-inflammation, which promotes venous thrombosis through several mechanisms, including leukocyte recruitment, remote signaling through thrombogenic microparticles, and platelet integrin activation." (PMID 35937062, 2022). "Using a murine model of venous thrombosis, the authors showed that systemic hypoxia is associated with the activation of the NLRP3 inflammatory complex and the production of IL-1β, which accelerates the development of venous thrombosis." (PMID 36014040, 2022). "Strikingly, IL-1β released from platelets mediates platelet activation cascade and promotes arterial thrombosis by acting on integrin αIIbβ3 outside to inside signal transduction." (PMID 35784685, 2022).
Thrombosis (continued). "The CANTOS (Canakinumab Anti-inflammatory Thrombosis Outcome Study) trial showed that the monoclonal antibody canakinumab directed against IL-1B was effective in reducing recurrent cardiovascular events in patients with prior MI and elevated CRP." (PMID 34722661, 2021). "More and more studies emphasize the role of inflammatory markers such as C-reactive protein and interleukin (IL)-1β, 6,8,10 in venous thrombosis." (PMID 32168924, 2020). "Canakinumab Anti-inflammatory Thrombosis Outcomes Study (CANTOS) has been provided the evidence that IL-1β treated as a target and reduced major cardiovascular events." (PMID 33071805, 2020). "We also observed a concomitant increase in the relative expression of NLRP3, caspase-1, interleukin-1β (IL-1β), and interleukin-18 (IL-18) transcripts in the individuals with clinically established venous thrombosis." (PMID 31653092, 2019). "Researchers have also found that individuals who develop venous thrombosis at high altitudes exhibit increased expression levels of IL-1β in the peripheral blood mononuclear cells." (PMID 31552036, 2019). "The pathogenic role of IL-1β is further confirmed by the recent Canakinumab Antiinflammatory Thrombosis Outcome Study, where targeting IL-1β led to a significantly lower rate of recurrent cardiovascular events." (PMID 30140264, 2018). "For example, previous study showed that the haplotype of IL1B, IL1RN, IL1R1, and IL1R2 increased the risk of venous thrombosis, and IL1/IL1Ra, CTLA-4 and Apo1/Fas genes polymorphisms associate with IgA nephropathy." (PMID 28881593, 2017). "Because of this, and evidence for cholesterol crystal-activated inflammasomes producing IL-1β, the Canakinumab Anti-inflammatory Thrombosis Outcomes Study (CANTOS) was instigated." (PMID 26139463, 2015). "The CANTOS (Canakinumab Anti-Inflammatory Thrombosis Outcomes Study) provided compelling evidence that targeting IL-1β with canakinumab, an IL-1β inhibitor, significantly reduced cardiovascular events independent of lipid levels, reinforcing the therapeutic potential of inflammation modulation." (PMID 40217801, 2025). "Additionally, NLRP3 inflammasome activation and IL-1β have been shown to promote atherogenesis and arterial thrombosis in preclinical animal models." (PMID 38267838, 2024). "Moreover, the Canakinumab Anti-inflammatory Thrombosis Outcome Study has demonstrated the beneficial effect of anti-inflammatory therapy targeting IL-1β on a recurrent cardiovascular event." (PMID 39100675, 2024). "The Canakinumab Anti-inflammatory Thrombosis Outcomes Study (CANTOS) demonstrated that targeting interleukin-1β (IL-1β) using canakinumabcan could significantly reduce the incidences of cardiovascular events." (PMID 38067137, 2023). "Furthermore, both IL-6 and IL-1β have been reported to be involved in thrombosis in SARS-CoV-2 infection." (PMID 36035409, 2022). "As the Canakinumab Anti‐inflammatory Thrombosis Outcome Study of 10 061 similarly overweight subjects with hsCRP > 2 mg/L has shown that treament with the IL‐1β neutralizing antibody canakinumab reduces CVD, we measured plasma IL‐1β concentrations in the overweight cohort." (PMID 33125159, 2021). "In addition, the genetic blockade of HIF-1α expression or IL-1β production decreased thrombus formation in a flow restriction-induced thrombosis model in rats." (PMID 31552036, 2019). "IL-1β induces the formation of blood platelet-leukocyte aggregates (PLAs), which suggests that IL-1β significantly affects the cross-talk between blood platelets and the immune response system, leading to coronary thrombosis." (PMID 28914761, 2017). "Furthermore, its success in the Canakinumab Anti-inflammatory Thrombosis Outcome Study trial revealed that IL-1β blockade also lowers cardiovascular event rates in patients with elevated inflammatory markers, highlighting the role of IL-1β in atherogenesis and systemic inflammation." (PMID 40307577, 2025).
Thrombosis (continued). "In addition, NLRP3 potentiates venous thrombosis in response to hypoxia upon IL-1β production." (PMID 31552036, 2019). "In contrast to IL-1β and FVIII, TNF-α and P-selectin were increased in lymphomas and DLBCL with thrombosis." (PMID 40076681, 2025). "Several studies have indicated a role for the NLRP3 inflammasome in venous thrombosis, including a central role for the combined NLRP3/IL-1β activity in VTE." (PMID 37753073, 2023). "Three of all the other four combinations to decrease the activation of Thrombosis included targeting TLR4, while the last one relied on the simultaneous blocking of IL-1β and IL-18." (PMID 36261775, 2022). "The Canakinumab Anti-inflammatory Thrombosis Outcome Study (CANTOS), another multicenter placebo-controlled trial, proved that IL-1β targeted therapy can prevent recurrent cardiovascular events to some extent." (PMID 35464772, 2022). "However, inactivation of STAT1 by such approaches may make individuals more prone to infection because of drastic effects on the inflammatory response, as has been shown recently in the case of inhibition of IL‐1β in The Canakinumab Anti‐inflammatory Thrombosis Outcome Study." (PMID 34569651, 2021). "The Canakinumab Antiinflammatory Thrombosis Outcome Study (CANTOS study) demonstrated that anti-inflammatory therapy with canakinumab, which targets IL-1β innate immunity pathway, resulted in a significant decreasing risk of recurrent cardiovascular events." (PMID 32467714, 2020). "DIC is an illness caused by an uncontrollable systemic activation of the clotting cascade due to pro-inflammatory cytokines, such as IL-1β, IL-6, and TNF-α, followed by excessive consumption of clotting factors, microvascular thrombosis, and finally, thrombotic or hemorrhagic episodes." (PMID 38254870, 2024). "Subsequent analysis of the Canakinumab Anti-inflammatory Thrombosis Outcome Study revealed that inhibiting IL-1β does not modify the plasmatic levels of IL-18." (PMID 37004526, 2023). "Interestingly, the levels of IL-1β and FGF-2 together with MCP-1, MIP-1α, and IP-10 were found to be related to thrombosis." (PMID 36012146, 2022). "Additionally, we detail the results of Canakinumab Anti-inflammatory Thrombosis Outcome Study (CANTOS), which showed that directly reducing inflammation with an IL-1β antagonist reduces cardiovascular event rates independent of LDL-C." (PMID 30873416, 2019). "Similarly, rheumatic mitral stenosis (MS) patients with clinically relevant thrombosis exhibited higher levels of IL-1β when compared to the individuals who did not experienced thrombosis." (PMID 38067137, 2023).
cryopyrin-associated periodic syndrome (108 papers, 2010 to 2025). Cryopyrin associated periodic syndrome (CAPS) defines a group of autoinflammatory diseases, characterized by recurrent episodes of systemic inflammatory attacks in the absence of infection or autoimmune disease. "Gain-of-function variants in the gene encoding NLRP3 (also called cryopyrin) lead to constitutive inflammasome activation and excessive IL-1β production in cryopyrin-associated periodic syndromes (CAPS)." (PMID 39930093, 2025). "The affinity of canakinumab to interleukin-1 beta granted this mAb FDA approval for potent inflammatory conditions including cryopyrin-associated periodic syndromes (CAPS) and systemic juvenile idiopathic arthritis (SJIA)." (PMID 39390211, 2024). "OI reduced IL-1β release induced by LPS in peripheral blood mononuclear cells (PBMCs) isolated from cryopyrin-associated periodic syndrome patients." (PMID 37730914, 2023). "Anakinra, a recombinant IL-1 receptor antagonist, blocks the interaction of IL-1β and IL-1α with its receptor and is indicated for RA and cryopyrin-associated periodic syndromes (CAPS)." (PMID 35214755, 2022). "Cryopyrin-associated periodic syndromes (CAPS) are diseases strongly associated with excessive IL-1β and IL-18 production." (PMID 35455985, 2022). "Uncontrolled IL-1β release can lead to autoinflammatory diseases such as Cryopyrin-associated periodic syndrome (CAPS) or Mediterranean fever." (PMID 32746880, 2020). "Consistent with the NLRP3 inflammasome role in interleukin (IL)-1β and IL-18 maturation, cryopyrinopathies are associated with excessive production of these cytokines." (PMID 30388107, 2018). "The role of IL-1β in rare autoinflammatory diseases, such as familial Mediterranean fever and cryopyrin-associated periodic syndrome, is long established using specific inhibitory strategies to prevent IL-1β activity." (PMID 30075804, 2018). "The dysregulated production of IL-1β by the NLRP3 inflammasome is the main reason for the development of Cryopyrin-Associated Periodic Syndromes (CAPS) which is caused by a mutation in NLRP3 gene." (PMID 27672241, 2016). "In vivo, neutralization of excessive IL-1β in cryopyrinopathies and in deficiency of interleukin-1 receptor antagonist (DIRA) results in decrease in IL-6 production." (PMID 25061439, 2014). "These cryopyrinopathies are associated with periodic fever, rashes, arthralgia, and conjunctivitis, and the aberrant production of IL-1β is the most prominent feature related to all these manifestations." (PMID 24273538, 2013). "IL-1β and IL-18 are the pivotal cytokines in autoinflammatory diseases such as cryopyrin-associated periodic syndromes (CAPS) group and Schnitzler syndrome (SchS) which are regularly associated with urticarial rash." (PMID 24490166, 2013). "Unlike normal mast cells that required stimulation with pro-inflammatory stimuli for IL-1β production, resident mast cells from cryopyrin-associated periodic syndrome patients constitutively produced IL-1β via the NLRP3 inflammasome." (PMID 22315529, 2010). "Mast cells were identified as the main cell population responsible for IL-1β in the skin of cryopyrin-associated periodic syndrome patients." (PMID 22315529, 2010). "A well-established causal relationship between gain of function mutations of NLRP3, resulting in excessive inflammasome activation with subsequent overproduction of IL-1β, and disease can be found for autoinflammatory conditions called cryopyrin-associated periodic syndromes (CAPS)." (PMID 35800898, 2022). "Mutated NLRP3 assembles a hyperactive inflammasome, which causes excessive secretion of interleukin (IL)-1β and IL-18 and, ultimately, a spectrum of autoinflammatory disorders known as cryopyrinopathies of which neonatal-onset multisystem inflammatory disease (NOMID) is the most severe phenotype." (PMID 30388107, 2018).
cryopyrin-associated periodic syndrome (continued). "Additionally, QUC inhibited IL-1β in Cryopyrin-Associated Periodic Syndromes (CAPS) macrophages, where NLRP3 inflammasome is constitutively activated." (PMID 28148962, 2017). "In light of the recent findings that connect autophagy and inflammasome regulation, it remains to be determined whether alterations in autophagy could explain, at least in part, the dysregulated production of IL-1β in NLRP3-associated cryopyrinopathies." (PMID 24273538, 2013). "A role of interleukin (IL)-1β has been suggested and IL-1 receptor antagonist anakinra was tried successfully in SS on the basis of its efficacy in treating some hereditary autoinflammatory syndromes, especially cryopyrin-associated periodic syndrome." (PMID 23527164, 2013). "Blood monocytes from patients with some of these disorders, especially cryopyrinopathies, readily release more IL-1β than monocytes from unaffected controls, revealing a loss of the tight control that regulates the processing and release of active IL-1β." (PMID 20195505, 2010). "Gain-of-function mutations in NLRP3 lead to constitutive inflammasome activation and excessive IL-1β production and are associated with the development of cryopyrin-associated periodic syndrome (CAPS)." (PMID 41087719, 2025). "For instance, gain-of-function mutations in the NLRP3 gene lead to uncontrolled inflammasome activation and excessive IL-1β production in cryopyrin-associated periodic syndromes (CAPS)." (PMID 41415279, 2025). "Cryopyrin-associated periodic syndrome (CAPS) is an autoinflammatory condition resulting from monoallelic NLRP3 variants that facilitate IL-1β production." (PMID 38321014, 2024). "In fact, LPS-stimulated human blood-derived macrophages and monocytes from patients with cryopyrin-associated periodic syndrome (CAPS) treated with OLT1177 presented a decreased level of IL-1β and IL-18." (PMID 37360532, 2023). "Anakinra is a recombinant form of human IL-1R antagonist, which blocks the signal transduction of both IL-1α and IL-1β and has been approved to treat active RA and cryopyrin-associated periodic syndromes (CAPS)." (PMID 33816637, 2021). "Canakinumab, brand name Ilaris, is a monoclonal antibody targeting IL-1β which has been approved for inflammatory condition such as cryopyrin-associated periodic syndromes (CAPS), since 2009." (PMID 35011965, 2021). "These biological molecules have been employed to manage cryopyrin-associated periodic syndromes (CAPS) as well as various maladies related to IL-1β." (PMID 34443594, 2021). "Cryopyrin-associated periodic syndrome (CAPS) is a rare autoinflammatory syndrome characterized by overproduction of interleukin (IL)-1β, resulting from dysregulated NOD-like receptor family pyrin domain containing 3 (NLRP3) inflammasome activity." (PMID 34099791, 2021). "NLRP3 gain-of-function mutation results in excessive release of IL-1β, giving rise to cryopyrin-associated periodic syndrome (CAPS), a group of rare hereditary autoinflammatory diseases." (PMID 32019187, 2020). "Specific mutations in diseases such as familial Mediterranean fever (FMF) and cryopyrin-associated periodic syndrome (CAPS) result in deregulated release of active IL-1β, which is clinically manifested as periodic fevers with systemic and local inflammation." (PMID 30459597, 2018). "Accordingly, NLRP3 gain-of-function mutations, which cause a spectrum of autoinflammatory disorders known as cryopyrin-associated periodic syndromes (CAPS), are associated with excessive IL-1β and IL-18 production." (PMID 30388107, 2018). "This includes the cryopyrin-associated periodic syndrome (CAPS) which is a rare inherited autoimmune disorder with a mutation in NLRP3 (CIAS1) gene that leads to overproduction of interleukin-1-beta (IL-1β)." (PMID 30574166, 2018). "In cryopyrin-associated periodic syndrome (CAPS), a group of rare diseases with an estimated prevalence of 1 in 360,000 persons, increased IL-1β activity plays a crucial role." (PMID 28109186, 2017).